JAM2 (junctional adhesion molecule 2)
Diseases named in the same sentence as JAM2 in open-access papers (continued):
Sharing a sentence is not in itself a finding about the gene and the disease.
tumor (21 papers, 2007 to 2026). "When we focused on different expressed genes in a pathway related to tumor development, there were some important oncogenes correlated with JAM2, such as JUN, MMP1, CDH1, and so on." (PMID 39838844, 2025). "The junctional adhesion proteins (JAMs) are involved in the formation of the tight junction, and lower expression of JAM2 has been associated with CRC disease progression, metastasis and poor prognosis, indicating JAM2 as a tumour suppressor." (PMID 33937029, 2021). "Numerous studies have shown that JAM2 played an important role in the metastasis of tumor cells." (PMID 39838844, 2025). "Furthermore, downregulation of JAM2 expression negatively paralleled with the increase of regional lymph node stage and tumor grade." (PMID 39838844, 2025). "Notably, BCAN, VCAN, and JAM2 were predominantly expressed by tumor cells, while ITGB1 was ubiquitously expressed across all clusters." (PMID 39554845, 2024). "JAM2 belongs to the JAMs family and immunoglobulin subfamily, and it has an essential role in maintaining the integrity of cell-cell junctions and regulating angiogenesis and proliferation of tumor cells." (PMID 37636389, 2023). "Tumor cells invade various tissues and organs accompanied by the disruption of TJ, which was in consistent with our sequence result that overexpression of JAM2 could active the mentioned pathways." (PMID 39838844, 2025). "Elevated HOTAIR levels can inhibit the activity of tumor suppressors such as protocadherin 10 (PCDH10), progesterone receptor (PGR), protocadherin β5 (PCDHB5), and junctional adhesion molecule 2 (JAM2), leading to tumorigenesis." (PMID 40129920, 2025). "JAM2, a member of the Junctional adhesion molecule (JAM) family, plays diverse roles in cell–cell contacts and tumor development." (PMID 39838844, 2025). "LncRNA HOTAIR interacts with PRC2 and induces H3K27me3-mediated repressive methylation on the promoter of tumor suppressive genes such as PTEN (phosphatase and tensin homolog) and JAM2 (junctional adhesion molecule B)." (PMID 36010595, 2022). "In more detail, SIGLEC17P expression could be used by Tregs to circulate among all tissues; CD33, PCDH1, JAM2, CDHR3, and ITGA3 would orchestrate migration/retention in NI TDLNs; CADM1 in I TDLNS; and CEACAM6 in tumor." (PMID 32601304, 2020). "SMAR1 also inhibited the expression of Fibronectin, Vinculin and JAM2 that are involved in promoting cell-extracellular matrix adhesion, cell spreading and migration, suggesting that SMAR1 might prevent tumor cell metastases through negative regulation of these proteins." (PMID 17668048, 2007).
cancer (18 papers, 2009 to 2025). A tumor composed of atypical neoplastic, often pleomorphic cells that invade other tissues. "The classification of annotated genes showed that the expression of JAM2 was mainly related to focal adhesion, phagosome, and neuroactive ligand–receptor interaction, especially in pathways in cancer." (PMID 39838844, 2025). "The results demonstrated that JAM2 was highly methylated in cancer tissues compared to normal tissues." (PMID 39838844, 2025). "JAM2 was downregulated in cancer samples than normal lung tissues." (PMID 39838844, 2025). "Although JAM2's expression and functions have been reported in various cancers, its clinical and biological significance in LUAD remains unclear." (PMID 39838844, 2025). "More studies suggested that JAM2 expression was different in various types of cancers." (PMID 33015704, 2020). "The integrative analysis identified PROX1+ LEC subsets, JAM2+ BECs, COL1A1+ stromal cells, PTPRC+ leukocytes, including MZB1+ plasmablasts, KRT19+ cancer cells, and MKI67+-proliferating cells." (PMID 41249124, 2025). "JAM-2 is known to be expressed on endothelial cells and hematopoietic stem cells (HSC), as well as cancer cells, and to play a role in various processes involving proliferation, adhesion, migration, and invasion." (PMID 33276815, 2020). "The abundance of genes related to vascular stability (CDH5, CLDN5, TIE1, JAM2, TEK) indicated that the group with a lower cholesterol score had higher vascular stability, while low vascular stability often promotes cancer growth." (PMID 38023262, 2023). "Interactions between junctional adhesion molecules (JAMs), including F11R, JAM2, and JAM3, are identified, and while their role during AV development is unknown, they are essential drivers of EMT in the context of cancer metastasis, modulating morphology, migration, and cell polarity." (PMID 37689753, 2023).
infection (6 papers, 2022 to 2024). The state of being infected such as from the introduction of a foreign agent such as serum, vaccine, antigenic substance or organism. "In NAc homogenates, enrichment analyses identified pathways related to immune modulatory pathways, including various types of infection (e.g., KRT14,16,17; HLA-B) and leukocyte migration (e.g., JAM2; PLCG1)." (PMID 37674018, 2023). "Before experimental infection (60 d of age), the expression levels of MUC-2 and JAM-2 were prominently upregulated (p < 0.05) in groups fed MSP at a level of 1 × 108 CFU/kg when compared with the control group (1.73- and 1.44-fold, respectively)." (PMID 36009671, 2022).
immune disorders (1 paper, 2024). "Jam-2 downregulation might have a positive effect on immune disorders, suggesting a role in disease pathophysiology." (PMID 38605366, 2024).
JAM2 also shares sentences with these, for which no sentence is quoted: adenoma (2 papers); breast tumor (2); hepatocellular carcinoma (2); melanoma (2); ocular sarcoidosis (2); pancreatic cancer (2); adenocarcinoma (1); Alzheimer disease (1); autoimmune hepatitis (1); Autoimmunity (1); behavioral disorders (1); Behçet’s disease (1); brain hemorrhages (1); cataract (1); chronic gastritis (1); colitis (1); dementia (1); encephalomyelitis (1); esophageal squamous cell carcinoma (1); fibrosis (1); gastric tumor (1); heart disease (1); holoprosencephaly (1); lung fibrosis (1); macular holes (1); metastatic cancer (1); neurodegenerative disease (1); neurodevelopmental disorder (1); non-small cell lung carcinoma (1); oral cancer (1).
A further 5 diseases each share a sentence with JAM2 in 1 paper.